TPTE (transmembrane phosphatase with tensin homology)
Description:
Could be involved in signal transduction.
Synonyms: CT44; PTEN2; TPTE1
Tractability: Antibody: UniProt predicts a signal peptide or a membrane-spanning region.
Gene: Protein-coding gene on chromosome 21 (10,521,553 to 10,606,140, forward strand). Ensembl gene ENSG00000274391.
Subcellular location: Membrane
Subcellular location (Human Protein Atlas): Cytosol; Endoplasmic reticulum
Pathways (Reactome):
Metabolism: Synthesis of PIPs at the Golgi membrane
Gene Ontology:
Molecular function: phosphatidylinositol-3,4,5-trisphosphate 3-phosphatase activity; protein tyrosine phosphatase activity; monoatomic ion channel activity; phosphatase activity
Biological process: protein dephosphorylation; signal transduction; monoatomic ion transmembrane transport; monoatomic ion transport; transmembrane transport
Cellular component: cytosol; membrane
Genetic constraint (gnomAD): Loss-of-function variants: 58 observed, 51.98 expected, observed/expected ratio (o/e) 1.12, 90% interval 0.9 to 1.39. The upper end of that interval is the gene's LOEUF score, 1.39, which puts it in group 5 of 6, group 1 being the genes least tolerant of losing a copy. Missense variants: 378 observed, 430.06 expected, observed/expected ratio (o/e) 0.88, 90% interval 0.81 to 0.96. Synonymous variants: 128 observed, 134.51 expected, observed/expected ratio (o/e) 0.95, 90% interval 0.82 to 1.1.
Homologues: Orthologues: rat Tpte2 (58% identical), mouse Tpte (58% identical), tropical clawed frog tpte2 (46% identical), zebrafish tpte (45% identical). Paralogues in human: TPTE2 (83% identical), PTEN (23% identical), TNS1 (18% identical), TNS3 (16% identical), TMEM266 (7% identical), HVCN1 (6% identical).
Diseases named in the same sentence as TPTE in open-access papers:
TPTE is named in the same sentence as 28 diseases in open-access papers, as found by Europe PMC text mining. Sharing a sentence is not in itself a finding about the gene and the disease. The quoted sentences say what the papers report.
melanoma (30 papers, 2017 to 2025). A malignant, usually aggressive tumor composed of atypical, neoplastic melanocytes. "Another cancer-associated gene found to have increased UV susceptibility in RB1 KO cells, and mutation rates in melanoma, is TPTE." (PMID 34983823, 2022). "While individualized mRNA vaccines encode for tumor- and host-specific antigens, BNT111 aims to induce expression of the four most frequent melanoma-associated antigens, NY-ESO-1, MAGE-A3, tyrosinase, and TPTE, again utilizing mRNA vaccine technology." (PMID 41012188, 2025). "The phase 2 trial BNT111-01 (NCT04526899) aims to assess the effect of a universal mRNA vaccine, BNT111, which encodes for four pre-specified proteins, NY-ESO-1, MAGE-A3, tyrosinase, and TPTE, in patients with unresectable melanoma." (PMID 41012188, 2025). "The RNA encodes four prevalent melanoma-associated antigens with high immunogenicity: NY-ESO-1, MAGE3, tyrosinase, and transmembrane phosphatase with tensin homology (TPTE)." (PMID 39696625, 2024). "TPTE was much less frequently expressed in young adult melanomas (3.2%, n = 1), whereas NY-ESO-1 and MAGE-A3 were more frequently expressed (both 19.4%, n = 6)." (PMID 38890171, 2024). "Our study highlights the expression profile of TPTE in pediatric and adult melanomas and describes TPTE as the second most frequently expressed TAA in pediatric melanomas after tyrosinase." (PMID 38890171, 2024). "Tyrosinase was expressed in all pediatric melanoma samples, followed in frequency by TPTE (44.0%, n = 11), MAGE-A3 (12.0%, n = 3), and NY-ESO-1 (8.0%, n = 2)." (PMID 38890171, 2024). "Based on IHC analysis, pediatric melanomas expressed tyrosinase (100.0%), TPTE (44.0%), MAGE-A3 (12.0%), and NY-ESO-1 (8.0%)." (PMID 38890171, 2024). "TPTE is poorly expressed in normal tissue, with expression mainly confined to the testis; however, expression in melanomas and other cancers has been reported." (PMID 36219477, 2023). "Using sequencing datasets from 1,970 melanomas, we found that cancers with RB1 pathway mutations, including CDKN2A/p16, have significant co-occurrence of mutations in TERT and TPTE." (PMID 34983823, 2022). "In a phase I clinical trial (NCT02410733), 119 melanoma patients were vaccinated with an RNA-LPX vaccine encoding the four melanoma TAAs MAGE-A3, transmembrane phosphatase with tensin homology (TPTE), NY-ESO-1 and tyrosinase." (PMID 33858437, 2021). "The RNA encoded for the melanoma antigens NY-ESO-1, MAGE-A3, tyrosinase, and TPTE (transmembrane phosphatase with tensin homology) and resulted in IFNα and antigen-specific T cell responses in all three patients." (PMID 29276510, 2017). "During the clinical study, the following TAAs for melanoma were utilized: New York esophageal squamous cell carcinoma 1 (NY-ESO-1), melanoma-associated antigen A3 (MAGE-A3), tyrosinase, and transmembrane phosphatase with tensin homology (TPTE)." (PMID 39171210, 2024). "Additionally, the use of liposomal RNA vaccines targeting melanoma-associated antigens NY-ESO-1, MAGE-A3, tyrosinase, and TPTE, have shown efficacy in melanoma tumor regression as monotherapy or in combination." (PMID 39682188, 2024). "Then, a phase I dose-escalation trial produced vaccines with RNA-lipoplexes encoding melanoma-associated malignant antigens, including New York-ESO 1 (NY-ESO-1), tyrosinase, melanoma-associated antigen A3 (MAGE-A3), and transmembrane phosphatase with tensin homology (TPTE) (NCT02410733)." (PMID 35456655, 2022). "Recently, promising clinical response was observed in melanoma patients who failed anti-PD1 treatment by using the of RNA-lipoplex vaccine (targeting four tumor associated antigens (TAA) namely NY-ESO-1, MAGEA3, tyrosinase and TPTE; FixVac)." (PMID 33937323, 2021).
melanoma (continued). "Additionally, BNT111, a liposomal RNA vaccine, targets four non-mutated tumor-associated antigens, including New York esophageal squamous cell carcinoma 1 (NY-ESO-1), tyrosinase, MAGE family member A3 (MAGE-A3), and transmembrane phosphatase with tensin homology (TPTE), in melanoma." (PMID 39789208, 2025). "BioNTech developed a cancer mRNA vaccine, called FixVac (BNT 111), targeting simultaneously four melanoma TAAs, including New York esophageal squamous cell carcinoma 1 (NY-ESO-1), melanoma-associated antigen A3 (MAGE-A3), tyrosinase, and transmembrane phosphatase with tensin homology (TPTE)." (PMID 39081320, 2024). "This vaccine is formulated with LPX as a vehicle and mRNAs that encode a fixed set of four melanoma-associated antigens (New York oesophageal squamous cell carcinoma 1 (NY-ESO-1), melanoma-associated antigen A3 (MAGE-A3), tyrosinase, and transmembrane phosphatase with tensin homology (TPTE))." (PMID 38169577, 2024). "A recent study in melanoma suggests that this may be possible: RNA-LPX vaccine encoding MAGEA3, NY-ESO-1, tyrosinase and transmembrane phosphatase with tensin homology (TPTE) were tested in checkpoint-inhibitor (CPI)-treated patients with unresectable melanoma." (PMID 32942747, 2020). "BNT111, a melanoma mRNA-lipoplex vaccine targeting four TAAs (NY-ESO-1, MAGE-A3, tyrosinase, and TPTE), has already demonstrated safety and immunogenicity in the phase I clinical trial, Lipo-MERIT for advanced melanoma patients." (PMID 41542091, 2025). "In our analysis of pediatric melanoma samples, we made several key findings regarding the expression of NY-ESO-1, tyrosinase, MAGE-A3, and TPTE." (PMID 38890171, 2024). "Young adult melanomas expressed tyrosinase (96.8%), NY-ESO-1 (19.4%), MAGE-A3 (19.4%), and TPTE (3.2%)." (PMID 38890171, 2024). "Adult melanomas expressed tyrosinase (86.2%), MAGE-A3 (75.9%), NY-ESO-1 (48.3%), and TPTE (48.3%)." (PMID 38890171, 2024). "The expression of TPTE has not been well studied in melanoma." (PMID 38890171, 2024). "The most promising trial data so far is from the BioNtech Lipo-MERIT trial in which patients with advanced melanoma were given 8 RNA-LPX vaccinations with a vaccine encoding four classic melanoma tumour antigens (NY-ESO-1, Tyrosinase, MAGE-A3, and TPTE) with or without anti-PD1." (PMID 38223410, 2024). "Additionally, Sahin and collaborators (2020) conducted phase I trials testing the melanoma liposomal RNA vaccine (BNT111) against four non-mutated antigens, including TPTE, Tyrosinase, melanoma-associated antigen A3 (MAGE-A3), and New York Esophageal Squamous Cell Carcinoma 1 (NY-ESO-1)." (PMID 38546751, 2024).
lung carcinoma (3 papers, 2019 to 2024). "The presence of TPTE protein has been detected in diverse cancer types, such as hepatocellular carcinoma, lung cancer, and ovarian cancer." (PMID 38546751, 2024). "TPTE is a germline-specific protein that is abnormally transcribed in cancers such as liver, prostate, and lung cancer." (PMID 38890171, 2024). "The cancer/testis antigen TPTE is aberrantly expressed in various tumors, including lung cancer, implicating its involvement in the immune responses against cancer cells." (PMID 38546751, 2024). "For instance, it has been demonstrated that TPTE is upregulated in prostate cancer, and autoantibody production against TPTE is observed in lung cancer." (PMID 31245297, 2019).
prostate carcinoma (3 papers, 2019 to 2024). A carcinoma that arises from epithelial cells of the prostate gland. "The current study, for the first time, examined the significance of TPTE expression in prostate cancer (PCa) tissues by generating a novel antibody marker targeting TPTE protein." (PMID 38546751, 2024). "Another example is TPTE (Transmembrane Phosphatase with Tensin Homology), whose gene is predominantly expressed in spermatocytes and in various cancers, such as prostate cancer and hepatocellular carcinoma." (PMID 37711387, 2023).
cutaneous melanoma (2 papers, 2022). A primary melanoma arising from atypical melanocytes in the skin. "TPTE is a relatively uncharacterized PTEN-related tyrosine phosphatase that is mutated in 26% of cutaneous melanoma." (PMID 34983823, 2022).
allergic disease (1 paper, 2022). An immune response that occurs following re-exposure to an innocuous antigen, and that requires the presence of existing antibodies against that antigen. "The TPTE gene is involved in signal transduction pathways, however, its specific role in allergic disease is not known." (PMID 34813682, 2022).
Arrhythmia (1 paper, 2014). Any cardiac rhythm other than the normal sinus rhythm. "Our results indicated that TpTe dispersion may be one of the reasons for arrhythmia caused by CO poisoning." (PMID 25000439, 2014).
autism (1 paper, 2015). Persistent deficits in social interaction and communication and interaction as well as a markedly restricted repertoire of activity and interest as well as repetitive patterns of behavior. "The identification of a rare maternally inherited variant in TPTE / PTEN in the proband is intriguing given the well-established role for PTEN in autism." (PMID 26076356, 2015). "This suggests rare variation in TPTE / PTEN2 may be involved in biological processes underlying head growth and perhaps autism pathogenesis." (PMID 26076356, 2015). "Exome sequencing of the family also identified a rare inherited variant predicted to disrupt splicing of TPTE / PTEN2, a PTEN homologue, which may likewise contribute to both macrocephaly and autism risk." (PMID 26076356, 2015). "Interestingly, TPTE / PTEN2 is a PTEN homologue, a gene in which mutations give rise to autism with macrocephaly." (PMID 26076356, 2015).
Azoospermia (1 paper, 2026). Absence of any measurable level of sperm,whereby spermatozoa cannot be observed even after centrifugation of the semen pellet. "The expression of TPTE is abnormally down-regulated in the testes of patients with non-obstructive azoospermia (NOA)." (PMID 41881971, 2026).
benign prostatic hyperplasia (1 paper, 2024). A non-cancerous nodular enlargement of the prostate gland. "Anti-TPTE-p2 antibody was then used to study the extent and pattern of TPTE expression in 102 PCa and 48 benign prostatic hyperplasia (BPH) tissue samples by immunohistochemistry." (PMID 38546751, 2024).
breast ductal carcinoma (1 paper, 2024). "Entirely new predictions include MAP3K21 (encoding a mixed-lineage kinase) in colorectal cancer, USP17L22 (encoding a deubiquitinating enzyme) in breast ductal carcinoma and TPTE (encoding a tyrosine phosphatase) in lung adenocarcinoma." (PMID 38890488, 2024).
Hypertension (1 paper, 2018). The presence of chronic increased pressure in the systemic arterial system. "The mechanism of FAM110A, PREP, ANKRD9, DCPS, WFDC12, TPTE, and LAMB2 genes on the occurrence and development of hypertension is not yet clear." (PMID 29379041, 2018).
pregnancy disorder (1 paper, 2025). A disorder that is related to pregnancy. "Specifically, GDM upregulated two genes in male fpEC that were previously linked to other pregnancy disorders, TPTE and NCAM2, respectively." (PMID 41288732, 2025).
Stroke (1 paper, 2022). Sudden impairment of blood flow to a part of the brain due to occlusion or rupture of an artery to the brain. "Four of these variants (TPTE rs143510517, MEP1A rs62619974, DDX31 rs142792732, and PATL1 rs79336999) were associated with stroke at p < 1 × 10−10." (PMID 36672803, 2022).
cancer (13 papers, 2003 to 2025). A tumor composed of atypical neoplastic, often pleomorphic cells that invade other tissues. "This multifaceted role extends to the association between elevated TPTE expression and enhanced survival outcomes, a phenomenon observed across various cancer types." (PMID 38546751, 2024). "The expression of TPTE in cancer cell lines was investigated through flow cytometric analysis in three specific cell lines (MCF-7 and PC-3)." (PMID 38546751, 2024). "Additional research is crucial to comprehensively understand and validate the specific functional mechanisms of TPTE in cancer development across diverse cancer types." (PMID 38546751, 2024). "In summary, this comprehensive study provides insights into the expression patterns of TPTE in PCa and BPH tissues, highlighting its potential associations with clinicopathological parameters and its impact on cancer cell viability." (PMID 38546751, 2024). "Two known testis-specific genes, FATE and TPTE, were identified to be restrictedly expressed in different cancers and normal testis." (PMID 12865919, 2003). "Both TPTE isoforms were expressed in normal testis and cancers, with the TPTE/BJ-HCC-5B being dominant in testis and the TPTE/BJ-HCC-5A dominant in cancers." (PMID 12865919, 2003). "Regulation of genes that are known to be associated with cancer (VEGFA, DDX58/RIG1, MST1R/RON, BAGE, and TPTE) in anti‐TIF‐1γ+ patients, and their expression on protein level, however, need further investigation as these genes are also involved in other biological processes apart from tumorigenesis." (PMID 34043263, 2021). "Consequently, there is a belief that TPTE, akin to PTEN, could exert a noteworthy influence on the progression of cancer." (PMID 38546751, 2024). "These two isoforms of TPTE cDNA might be caused by different splicing, and the splicing machinery might be regulated by different factors that resulted in the TPTE/BJ-HCC-5B dominantly expressed in testis and the TPTE/BJ-HCC-5A dominantly expressed in cancer tissues." (PMID 12865919, 2003). "Finally, we applied this TCR identification approach to the transmembrane phosphatase with tensin homology (TPTE), which belongs to a large group of antigens with high cancer cell selectivity, for which spontaneous T-cell responses have not yet been reported in cancer patients." (PMID 26140230, 2015).
tumor (9 papers, 2003 to 2025). "Understanding the intricate TPTE signaling pathways involved in PCa provides potential diagnostic tumor marker to intervene in disease progression." (PMID 38546751, 2024). "To investigate the expression of TPTE as a specific tumor marker in PCa tissues, we conducted immunohistochemical analysis." (PMID 38546751, 2024). "Herein, we demonstrated that FATE and TPTE mRNA transcripts were expressed in different histological types of tumours and normal testis." (PMID 12865919, 2003). "The literature also indicates that TPTE, INMT, and STAR are differentially expressed in tumours and may be associated with prognosis." (PMID 36818393, 2023). "In view of the fact that many tumour-derived missense mutations were observed in PTEN resulting in cell cycle progression and inhibition of apoptosis, the TPTE/BJ-HCC-5A and TPTE/BJ-HCC-5B may be involved in the survival of tumour cells." (PMID 12865919, 2003).
infection (1 paper, 2019). The state of being infected such as from the introduction of a foreign agent such as serum, vaccine, antigenic substance or organism. "No statistical difference was found in cause of death between patients withnormal and prolonged TpTe.However, there was a trend of increased mortality from infection in patientswith normal TpTe (p = 0.09)." (PMID 30118535, 2019).
TPTE also shares sentences with these, for which no sentence is quoted: Brugada syndrome (2 papers); esophageal squamous cell carcinoma (2); hypertrophic cardiomyopathy (2); long QT syndrome (2); breast carcinoma (1); breast tumours (1); colorectal cancer (1); Esophageal (1); hepatocellular carcinoma (1); leukemia (1); lung adenocarcinoma (1); myocardial infarction (1).